GBP1 (guanylate binding protein 1)
Diseases named in the same sentence as GBP1 in open-access papers (continued):
Sharing a sentence is not in itself a finding about the gene and the disease.
infection (continued). "After infection of T. gondii, mGbp2B (also named Gbp1) can activate inflammasome complex signaling cascades, which leads to Nlrp1, Nlrp3, Nlrp4, and pro-caspase-1 degradation resulting in converting the cell death type from pyroptosis to apoptosis." (PMID 32731337, 2020). "Mice lacking GBP2, GBP5, or multiple GBPs on chromosome 3 (GBP2, GBP2b (GBP1), GBP3, GBP5, GBP7) were significantly more susceptible to infection, revealing a critical role for these proteins in restricting bacterial infection." (PMID 32150572, 2020). "We also found that during STm infection, IFNγ enhanced macrophage pyroptosis in a GBP1‐dependent manner." (PMID 31268602, 2019). "GBP1 is a unique large GTPase governing cellular responses to infection, inflammation, and environmental stressors that, in some contexts, can be hijacked by upstream oncogenic events to induce treatment resistance and tumor progression in cancer." (PMID 32117203, 2019). "LPS transfection of MDMs and THP‐1 (Fig EV5C) led to GBP1‐independent pyroptosis which was in contrast to the role of GBP1 during natural infection with STm." (PMID 31268602, 2019). "We therefore propose that PV targeting is required for GBP1‐dependent apoptosis during Tg infection." (PMID 31268602, 2019). "This suggested that targeting of microbial vacuoles and the same molecular functions of GBP1 were required to mediate apoptosis during Tg infection and pyroptosis during STm infection." (PMID 31268602, 2019). "Together with our results on Tg infection, these findings pointed toward a broader role for GBP1 in host cell death during microbial infections." (PMID 31268602, 2019). "Our studies uncover a gatekeeping role for human GBP1 and expand the role of human GBPs in regulating other forms of cell death during natural infection by microbial pathogens." (PMID 31268602, 2019). "In infection, these attributes of GBP1 cooperate to prevent proliferation of infected cells, stymy premature angiogenesis, and protect stroma from inflammation-induced apoptosis while coordinating cell-autonomous immunity functions including autophagocytosis." (PMID 32117203, 2019). "Taken together, these experiments established that human GBP1 was required for macrophage cell death in response to infection by type I or type II Tg and its GTPase activity and isoprenylation were essential for this function." (PMID 31268602, 2019). "To better understand common determinants of GBP1 in influencing host cell death responses to infection, we investigated its role during STm infection." (PMID 31268602, 2019). "We tested the involvement of GBP1 in these processes by RNAi in primary MDMs and infection of THP‐1 ΔGBP1 cells." (PMID 31268602, 2019). "This indicated that, like in the context of apoptosis, the role of GBP1 was restricted to regulating infection‐induced cell death." (PMID 31268602, 2019). "Analysis of global gene expression of bone marrow derived macrophages from BALB/c mouse demonstrated upregulation of expression of Gbp2b/Gbp1, Gbp2, Gbp3, Gbp6, and Gbp7 after 24 hours of infection with Leishmania major promastigotes." (PMID 29467757, 2018). "Five of them (GBP1 to 5) were expressed in hMDMs and their expressions were strongly induced upon infection with F. novicida." (PMID 29339744, 2018). "To do that, we treated Scr and Gbp1 Kd macrophages with Staphylococcus aureus (S. aureus) for 1-hour infection." (PMID 29374208, 2018). "The increased expression of Gbp2b/Gbp1 and Gbp5 in clinically asymptomatic mice reveals the price exacted from the organism by a dormant infection." (PMID 29467757, 2018). "In liver, infection induced significant increases of Gbp2b/Gbp1 mRNA in strains of CcS/Dem series, CcS-5, and CcS-16." (PMID 29467757, 2018). "Most of previous studies primarily focused on the role of Gbp1 in regulating innate immunity of macrophages to defend against pathogen infections." (PMID 29374208, 2018).
infection (continued). "Infection increased the expression of Gbp2b/Gbp1 and Gbp5 in organs of tested mice, the highest increase was observed in skin." (PMID 29467757, 2018). "We identified and confirmed that Gbp1 and Gbp2 are ubiquitinated in WT MEFs in a Toxoplasma-infection independent fashion." (PMID 29510761, 2018). "Nevertheless, we identified and confirmed Gbp1 and Gbp2 as being ubiquitinated in a Toxoplasma-infection independent manner." (PMID 29510761, 2018). "Infection with either strain increased expression of ISGs (GBP1, IFIT1, IRF7) and reduced expression of lymphocyte related genes (CD3D, CD8A, ZAP70)." (PMID 28852031, 2017). "Upon infection, both WT bacteria and S. flexneri ΔipaH9.8 became coated with GBP1, a status that, once established, was sustained throughout division by bacteria of either strain." (PMID 29024643, 2017). "Overexpression of RIG-I or MAVS in guinea pig JH4 cells restricted H5N1 viral replication and significantly increased GBP- 1 expression following infection." (PMID 28418930, 2017). "RIG-I and MAVS overexpression resulted in marked increase of Mx1 and GBP-1 at both 12 and 24 hours post-infection when compared to H5N1-infected control cells." (PMID 28418930, 2017). "Here, we show that the human protein GBP1 acts as a cytosolic “glue trap,” capturing cytosolic Gram-negative bacteria through a unique protein motif and preventing disseminated infections in cell culture models." (PMID 29233899, 2017). "GBP1, induced by interferon, is involved in early activation of immune response to pathogen infection." (PMID 28830381, 2017). "IFN-inducible guanylate binding protein (GBP) 1 and 2 (also known to be regulated by interferon) were also significantly different (as determined by Progenesis) between day 7 post-infection and day 5 post-infection." (PMID 27311020, 2016). "The inhibitory roles and antiviral mechanisms of GBP1 depend on the nature of the pathogen and the infection model." (PMID 26889038, 2016). "To assess the requirement of IRG proteins in the recruitment of Gbp1 to susceptible parasites, we examined accumulation of Gbp1, Irgb6, and Irga6 to Δrop5 parasites in Irgm3−/−vs. wild type (C57BL/6) BMM at 2 hr post infection." (PMID 23633952, 2013). "While, more work are still needed to address the role and mechanisms of GBP1 in different infection models especially for viruses." (PMID 23186538, 2012). "The expression levels of selective anti-viral cytokines were decreased in Gbp1 siRNA treated cells, while the transcription factor activity of NF-κB was impaired upon GBP1 silencing during infection." (PMID 23186538, 2012). "We studied the behavior of murine GBP1 (mGBP1) upon infection with T. gondii in vitro and confirmed that IFN-γ-dependent re-localization of mGBP1 to the parasitophorous vacuole (PV) correlates with the virulence type of the parasite." (PMID 21931713, 2011). "We used CRISPR–Cas9-engineered HeLa GBP1 KO cells stably expressing mCherry–GBP1 variants under a Tet-inducible promoter (HeLa ∆GBP1 + Tet-mCherry-GBP1) cells for infection with mCerulean3-expressing S. Typhimurium and quantified coat density on cytosolic bacteria at 2 h after infection." (PMID 39394410, 2025). "Thus, the levels of various pro‐ and anti‐inflammatory cytokines and chemokines are differently impacted in HIF1‐KD and GBP1‐KD macrophages after infection with HN878 or CDC1551." (PMID 41287823, 2025). "Thresholded self-assembly may, thus, prevent GBP1 coat formation on endogenous membranes under homeostatic conditions, activating only during infection." (PMID 39394410, 2025).
infection (continued). "The study demonstrates that GBP1 is associated with the NOD-like receptor signaling pathway, utilizing an extended conformation to interact with bacterial membranes and initiate the innate immune response to infection." (PMID 41099523, 2025). "Indeed, infected Acod1−/− mice expressed higher mRNA levels of Il6, IFNγ, Nos2 and Gbp1 than wild‐type controls in the lungs, but also in the spleen, after intratracheal infection." (PMID 36479617, 2023). "The mRNA levels of all representative genes were decreased in GBP1-overexpressing cells, which suggests that GBP1 might function at the beginning of infection." (PMID 36918936, 2023). "To determine whether mGBP1 could modulate IAV‐induced inflammasome activation, we infected primary WT, NLRP3−/− and GBP1−/− BMDMs with IAV [multiplicity of infection (MOI) 25] for 16 h." (PMID 36744765, 2023). "Human GBP1 associates with damaged endosomes and lysosomes in the absence of infection, although the mechanism underlying how GBP1 binds ruptured host membranes is unclear." (PMID 37737612, 2023). "For instance, GBP1 is produced in response to infections with IAV, CSFV, and HCV." (PMID 36918936, 2023). "It is also possible that other GBPs or host factors, might play a concerted role with GBP1 during infection." (PMID 35663470, 2022). "Indeed, re‐expression of GBP1 (THP‐1 ∆GBP1 + Tet‐GBP1 cells) restored cell death in response to Tg infection, which provided additional support for siRNA and CRISPR/Cas9‐based experiments and underscored the role of GBP1 in cell death." (PMID 31268602, 2019). "All tested strains except CcS-5 and OcB-9 exhibited significantly higher expression of Gbp2b/Gbp1 and Gbp5 in skin after infection, irrespective of their susceptibility or resistance status." (PMID 29467757, 2018). "However, certain ISGs (e.g. guanylate binding protein 1, 2, 3 and 6 (GBP1, 2, 3 and 6)) have higher expression levels following infection with the H5N3 virus than the other two isolates." (PMID 28558796, 2017). "However, our qRT-PCR results show that GBP1 is upregulated at the transcriptional level in PK-15 cells and in pigs after infection with Shimen, which is consistent with the results of microarray expression profiling." (PMID 26889038, 2016). "Similarly, type III parasites expressing a kinase-active version of ROP18 (i.e. CTG+ROP18) avoided accumulation of Gbp1 over the first two hr post infection." (PMID 23633952, 2013). "Therefore we examined the ability of activated wild type (C57BL/6) or Gbp1−/− BMM to restrict the intracellular replication of T. gondii at 20 hr post infection." (PMID 23633952, 2013). "Since NF-κB can be activated upon a broad range of pathogen infection, this could be a common action for GBP1 to play its role in different infection models." (PMID 23186538, 2012). "GBP-1 is the best-characterized member of the GBP family and mediates cellular responses to IFN-γ in infection and inflammation, suggesting that GBP-1 may be an important component of the innate immune response." (PMID 21151871, 2010). "They further suggested that IL-10 and GBP1 might inhibit the activation of caspase-3 and lead to the attenuation of macrophage apoptosis, thereby fostering the intracellular survival of mycobacteria and establishment of infection." (PMID 35773466, 2022). "The NF-κB downstream signaling induced the IL-10 and GBP-1 might be inhibited the activation of caspase-3 and leads to attenuate the macrophages apoptosis, thereby fostering its intracellular survival of mycobacteria and establishment of infection." (PMID 32117813, 2020).
infection (continued). "GBP1 plays an essential role in cell-autonomous immunity, in which infected cells rely upon maturation of phagosomes/infected vacuoles into autophagosomes to destroy invading pathogens or, if this cannot clear the infection, pyroptosis to trigger increased immunity at the site of infection." (PMID 32117203, 2019). "Like other members of the dynamin family of large GTPases, which are also involved in cell-autonomous immunity, GBP1 appears to cooperate with numerous membrane regulatory elements, such as phagocyte oxidase and p62/sequestosome 1, which promote effective autophagy and infection control." (PMID 32117203, 2019). "However, the levels of IFN-γ and GBP1 in both mice were similar on 7 d post-infection (P > 0.05)." (PMID 27644341, 2016). "Furthermore, Gbp1 was important for resistance to challenge with an intermediate virulence, type II strain of T. gondii, with the majority of mice succumbing after the initial acute infection." (PMID 23633952, 2013). "However, the distinct role of GBP1 during infection of other pathogens, including mosquito-borne flaviviruses remains largely unknown." (PMID 23186538, 2012). "Although the bacterial load was higher in HN878‐infected HIF1‐KD and GBP1‐KD, compared with CDC1551 infection, the difference was significant only in GBP‐KD at 96 hpi." (PMID 41287823, 2025). "We then infected ∆GBP1 + Tet-mCherry-GBP1 cells transiently expressing GFP–Nb74 with S. Typhimurium and imaged GBP1 coat formation at 2 h after infection using confocal microscopy." (PMID 39394410, 2025). "To validate this up-regulation, we quantified the expression of IL6, GBP1, GBP2 and ISG15 in the same infection condition as bulk RNA-seq by qPCR." (PMID 39777915, 2025). "Interferon-induced transmembrane protein 3 (IFITM3) and guanylate-binding proteins 1 and 4 (GBP1 and GBP4) show minimal expression in controls but are significantly upregulated in the moderate infection, indicating a strong antiviral response." (PMID 39928675, 2025). "Guanylate binding protein 1 (GBP1) is the most concerned member of the GBP family, which has a series of effects such as anti-infection and anti-angiogenesis." (PMID 38167153, 2024). "GBP1 is a GTPase primarily induced by interferon-γ (IFN-γ) and involved in processes such as infection and inflammation." (PMID 39715172, 2024). "Furthermore, human GBP1 associates with ruptured host vacuoles in the absence of infection, indicating that human GBPs may be capable of associating with host-derived bacteria-containing vacuoles, similar to mouse GBPs." (PMID 37737612, 2023). "Furthermore, human GBP1 associates with ruptured host vacuoles in the absence of infection." (PMID 37737612, 2023). "Collectively, these data indicate that human GBP1 is required for IFN-γ-primed inflammasome responses in both hMDMs and THP-1 cells during infection with T4SS+ Lp." (PMID 37737612, 2023). "In M2 macrophages, genes associated with an inflammatory profile were more extensively upregulated by infection with rBCG-LTAK63, compared to infection with BCG, including the TAP1 and GBP1 genes, which are both part of the IFN signaling pathway." (PMID 35746439, 2022). "Guanylate binding protein 1 (GBP1) and guanylate binding protein 5 (GBP5) are two member of the GBP family and mediate cellular response to IFNγ in infection and inflammation." (PMID 35187081, 2022). "We show that mouse GBP1 and GBP3 are specifically required for inflammasome activation during infection with the cytosolic bacterium Francisella novicida." (PMID 35906252, 2022). "GBP1 activation provoked by IFN and other cytokine stimulation involves cellular responses to infection and inflammation by preventing the proliferation of infected, endothelial, and epithelial cells and protecting cells from apoptosis." (PMID 35222540, 2022). "Guanylate-binding protein 1 (GBP1) is an interferon (IFN)-inducible guanosine triphosphatases (GTPases) involving inflammation and infection." (PMID 35222540, 2022).
infection (continued). "Early studies showed that the ectopic expression of GBP1 resulted in reduced viral progeny upon the infection of vesicular stomatitis virus (VSV), encephalomyocarditis virus (EMCV), or dengue virus, while knockdown of GBP1 facilitated viral replication." (PMID 33673837, 2021). "We silenced individual GBP1–5 by siRNA transfection (Fig EV1C) and quantified type I and type II Tg infection‐induced cell death." (PMID 31268602, 2019). "GBP1 is a member of the IFNγ-inducible GBP family, whose members are protective against bacterial and parasite infection." (PMID 30303482, 2018). "GBP-1 knockdown in cells overexpressing RIG-I resulted in significantly reduced induction of Mx1 mRNA at 12 and 24 hours post infection, whereas Mx1 expression in H5N1 infected cells overexpressing MAVS was not affected by GBP-1 knockdown." (PMID 28418930, 2017). "Hence, the increased susceptibility in Gbp1−/− or Gbp2−/− mice to chronic infection may reflect reduced NO production locally within the CNS, or result from impaired clearance via the IRG or GBP pathways, leading to higher chronic burdens of infection." (PMID 23633952, 2013). "Genes that were induced during the first 2 days after infection included early stress response genes (early growth response, Fos, Jun) and IFN responsive genes (MX1 and 2, STAT-1, IFN-γ inducible protein-10, guanylate binding protein-1 and -2)." (PMID 17725815, 2007). "Compared with Mtb‐infected control macrophages, the level of IL1β was significantly reduced in both HIF1‐KD and GBP1‐KD cells after infection with HN878 or CDC1551, while TNFα and IL6 were significantly reduced only in HN878‐infected HIF1‐KD and GBP1‐KD macrophages." (PMID 41287823, 2025). "A significant downregulation of HIF1A, NLRP3, GBP1 and ASC, and upregulation of IL1B was observed in HIF1A‐KD macrophages, while downregulation of ASC was noted in GBP1‐KD macrophages infected with HN878, compared with CDC1551 infection." (PMID 41287823, 2025). "Of interest, a cluster of mouse GBPs, including GBP1, did not demontrate significant antiviral activity in a mouse model of infection." (PMID 40952259, 2025). "In summary, we unraveled a novel mechanism of inflammasome activation mediated by GBP1 and HIF‐1α, which orchestrates differential immune response in macrophages and in vivo upon infection with Mtb strains that cause a progressive or nonprogressive infection." (PMID 41287823, 2025). "We observed that Gbp1−/− mice were highly protected against A. baumannii 1605 infection with > 70% survival rate, although with no reduction in bacterial burden but a strong reduction in plasma pro-inflammatory cytokine levels." (PMID 39533032, 2024). "Upon infection, viral genome copies were decreased in the cells overexpressing GBP1, compared to that in the cells without GBP1 overexpression." (PMID 36918936, 2023). "Supporting this finding, we did not observe degradation of PIM1 or dephosphorylation of GBP1 upon STm-infection." (PMID 37797010, 2023). "Importantly, we found that WT, Gbp1–/–, Gbp2–/–, Gbp3–/–, Gbp5–/–, and Aim2–/– BMDMs all released similar levels of IL-1β, IL-18 and LDH in response to infection with F. novicida in the presence of E. coli LPS." (PMID 35906252, 2022). "To investigate whether individual GBPs are responsible for IRGB10 recruitment, we overexpressed IRGB10 and one GBP at a time (GBP1, GBP2, GBP3, GBP5 or GBP7) in LA-4 cells followed by infection with F. novicida." (PMID 35906252, 2022). "The results showed that as the infection progressed, viral RNA was gradually increased, but the mRNA expression level of GBP1 was significantly decreased, confirming the negative correlation between GBP1 expression and viral replication." (PMID 35937300, 2022). "In addition, six genes (SLFN12, MX2, TRIM30A, GBP1, GBP6, and IFIH1) were common to 15 dpi and the early infection period." (PMID 29147886, 2018).